ENSG00000267173 (novel protein)
Gene: Protein-coding gene on chromosome 19 (44,329,695 to 44,401,608, reverse strand). Ensembl gene ENSG00000267173.
Genetic constraint (gnomAD): Loss-of-function variants: 8 observed, 19.48 expected, observed/expected ratio (o/e) 0.41, 90% interval 0.24 to 0.74. Missense variants: 160 observed, 183.68 expected, observed/expected ratio (o/e) 0.87, 90% interval 0.76 to 0.99. Synonymous variants: 57 observed, 65.87 expected, observed/expected ratio (o/e) 0.87, 90% interval 0.7 to 1.08.